ANLN (anillin, actin binding protein)
Diseases named in the same sentence as ANLN in open-access papers (continued):
Sharing a sentence is not in itself a finding about the gene and the disease.
lung carcinoma (34 papers, 2011 to 2026). "ANLN encodes an actin-binding protein essential for cytokinesis and has been implicated in lung cancer progression." (PMID 41477124, 2025). "E2F7 and ANLN, were both involved in the cell cycle process and associated with cell proliferation in malignancy lung cancer." (PMID 38711158, 2024). "Recent studies have implicated ANLN in various cancers, such as pancreatic cancer, gastric cancer, breast cancer, lung cancer, liver cancer, bladder cancer, colorectal cancer and other malignant tumors." (PMID 38398143, 2024). "The cBioPortal (TCGA, Pan-Cancer Atlas) database showed that lung cancer had the highest frequency of ANLN mutation (≈ 23.68%)." (PMID 35991576, 2022). "In our study, lung cancer showed the highest frequency of ANLN alterations (≈ 23.68%); moreover, amplification and mutation were the most common genetic alterations." (PMID 35991576, 2022). "Previous studies have suggested that ANLN expression is elevated in most human cancers and is associated with poor clinical outcomes in patients with breast, bladder, colorectal, and lung cancers." (PMID 32258155, 2020). "ANLN-associated pathways may represent potential therapeutic targets in lung cancer." (PMID 42074579, 2026). "Functional experiments showed that ANLN deletion reduced proliferation and promoted apoptosis in lung cancer cells." (PMID 42074579, 2026). "Studies have shown that, miR-195-5p, identified in lung cancer brain metastasis, can inhibit ANLN expression, leading to G0/G1 cell cycle arrest, promoting apoptosis, and significantly reducing the invasion and migration abilities of LUAD cells." (PMID 41573677, 2025). "ANLN is highly expressed in lung cancer and plays a crucial role in the malignant progression of tumors through multiple pathways." (PMID 41573677, 2025). "Overexpression of ANLN was significantly associated with clinical factors such as age, gender, TNM stage, and pathological grade of lung cancer patients." (PMID 41573677, 2025). "Our study has shown that suppression of miR-195-5p/-3p expression and overexpression of the ANLN/MAD2L1 genes are among the factors that accelerate the progression of lung cancer cells." (PMID 40723231, 2025). "For example, in lung cancer, the knockdown of ANLN can activate pyroptosis and inhibit the progression of lung adenocarcinoma." (PMID 38398143, 2024). "Through the HPA database, we found that ANLN was strongly positive in the immunohistochemical test of lung cancer tissues." (PMID 37007961, 2023). "ANLN expression was essential for the growth of lung cancer cell lines, as well as the maintenance of cellular motility and cytokinesis." (PMID 35444699, 2022). "ANLN played a key role in human lung cancer by participating in phosphoinositide 3-kinase/AKT pathway." (PMID 36543847, 2022). "The expression of ANLN is up-regulated in a variety of types of tumors, including lung cancer, and the development of cancers is related to the expression level of ANLN." (PMID 34416861, 2021). "There was evidence showing that ANLN was involved in cancer progression, including pancreatic cancer, colorectal cancer and lung cancer." (PMID 34743685, 2021). "To date, many studies have emphasized the involvement of ANLN in cancer progression, including pancreatic, colorectal, breast, and lung cancers." (PMID 32560530, 2020). "High ANLN mRNA expression and nuclear ANLN protein expression in lung cancer tissue has been shown to be significantly correlated to poor survival." (PMID 27863473, 2016). "Our data are supported by a report that siRNAs against ANLN suppress growth, induce apoptosis, and inhibit migration in lung cancer cells." (PMID 26486082, 2015). "The over-expression of ANLN has been reported to be a biomarker for pancreatic carcinoma, and predicted for poor survival in early lung cancers." (PMID 21679412, 2011). "In lung cancer, ANLN downregulation induces G0/G1 arrest and enhances apoptosis." (PMID 41573677, 2025).
lung carcinoma (continued). "In lung cancer, ANLN enhances proliferation and suppresses apoptosis through AKT phosphorylation." (PMID 41573677, 2025). "In addition to its roles in enhancing cell proliferation, migration, and EMT, and activating pathways such as PI3K/AKT and RhoA, ANLN has also been found to promote lung cancer progression by inhibiting pyroptosis." (PMID 41573677, 2025). "Additionally, as a downstream effector of RhoA GTPase, ANLN activates RhoA-mediated signaling to enhance actomyosin contractility, a mechanism recognized as essential for promoting lung cancer cell migration and invasion." (PMID 41573677, 2025). "Additionally, lung cancer patients with high ANLN expression had shorter overall survival(OS), disease-free interval(DFI), and progression-free interval(PFI) compared to those with lower expression levels." (PMID 41573677, 2025). "Knockdown assays targeting ANLN expression revealed dramatically reduced aggressive phenotypes (cell growth, migration, and invasion) of cancer cells, including pancreatic, breast, and lung cancers." (PMID 40723231, 2025). "ANLN regulated PI3K/Akt signaling in lung cancer and promoted cancer progression." (PMID 34082790, 2021). "Moreover, it has been reported that nuclear ANLN protein expression in lung cancer tissue is significantly correlated with poor survival." (PMID 32536039, 2020). "The inhibition of ANLN expression suppressed the growth of lung cancer cells in culture." (PMID 32560530, 2020). "ANLN has also been found to play a key role in the development of human lung cancer." (PMID 31681575, 2019). "Interestingly, previous study reported that PI3K/AKT signaling promoted the malignant potential of lung cancer cells by regulating ANLN nuclear localization and stability." (PMID 31395079, 2019). "However, whether plasma-based ANLN testing can contribute to the diagnosis of lung cancer as well as the mechanisms by which ANLN influences tumor-associated immune infiltration, remain subjects requiring further investigation." (PMID 41573677, 2025). "ANLN was subsequently evaluated in independent single-cell datasets, followed by functional validation using CRISPR-Cas9-mediated gene knockout in lung cancer cells." (PMID 42074579, 2026). "Other genes, including PLK1, CDCA8, ANLN, and RACGAP1, were all discovered to play different roles in proliferation, metastasis, and enhanced chemotherapy sensitivity to doxorubicin in lung cancer." (PMID 35464867, 2022). "Analyses of tumor mRNA expression profiles from the TCGA database and ANLN protein expression data from the HPA database revealed that ANLN expression levels in lung cancer tissues were significantly higher than those in adjacent normal tissues." (PMID 41573677, 2025). "Previous studies have shown that the high expression of ANLN predicts poor prognosis in renal cell carcinoma, liver cancer, and lung cancer, but no one has reported its role in rectal cancer." (PMID 35548187, 2022).
pancreatic cancer (31 papers, 2011 to 2026). "ANLN expression is significantly upregulated in pancreatic cancer tissues and cell lines and is associated with tumor size, differentiation, TNM stage, lymph node metastasis, distant metastasis, and poor prognosis in pancreatic cancer." (PMID 38144520, 2023). "The ROC curve analysis revealed that the MIR600HG/hsa-miR-342-3p/ANLN-related risk model effectively predicted the 1-year, 3-year, and 5-year survival rates of patients with pancreatic cancer based on TCGA dataset." (PMID 37741887, 2023). "It is reported that ANLN participates in the HMGA2-induced increase in the tumorigenicity of pancreatic cancer cells and through controlling the EZH2/miR-218-5p/LASP1 axis, ANLN deficiency dramatically reduces pancreatic tumor cell migration and invasion." (PMID 36199577, 2022). "In pancreatic cancer, ANLN deficiency led to the expression of miR218-5p while mir-218 caused the apoptosis of pancreatic cancer cells." (PMID 32560530, 2020). "The expression of ANLN and its association with pancreatic cancer patient survival were analyzed using an online database and confirmed by immunohistochemistry." (PMID 31395079, 2019). "We subsequently analyzed the association between the ANLN expression and clinicopathological features in 80 pancreatic cancer samples." (PMID 31395079, 2019). "The present study demonstrated that ANLN was upregulated in pancreatic cancer, and upregulated ANLN was associated with a poorer outcome in patients with pancreatic cancer." (PMID 31395079, 2019). "ANLN expression was increased in pancreatic cancer, and high ANLN expression was associated with a poor prognosis in the pancreatic ductal adenocarcinoma TCGA database." (PMID 31395079, 2019). "Kaplan-Meier analysis showed that upregulated ANLN expression was significantly associated with shorter survival for patients with pancreatic cancer (P = 0.001)." (PMID 31395079, 2019). "In functional assays, EZH2 restoration in pancreatic cancer cells transfected with ANLN RNAi rescued the inhibition of cell proliferation, colony formation, cell migration and cell invasion caused by ANLN knockdown." (PMID 31395079, 2019). "We construct a risk score containing ANLN, previous studies have found that the expression of ANLN is closely related to immune infiltration, so we explored whether the risk score containing ANLN can affect immune infiltration of pancreatic cancer." (PMID 37741887, 2023). "In addition, we constructed a prognostic risk model for pancreatic cancer based on the MIR600HG/hsa-miR-342-3p/ANLN network score." (PMID 37741887, 2023). "A high expression level of ANLN was associated with poor prognosis of pancreatic cancer patients." (PMID 31395079, 2019). "We explored whether the MIR600HG/hsa-miR-342-3p/ANLN network could be used as an indicator to evaluate the prognosis of patients with pancreatic cancer by investigating the association of the RNA network and OS in patients with pancreatic cancer using a multivariate Cox regression analysis." (PMID 37741887, 2023). "In pancreatic cancer, ANLN depletion downregulates multiple cell-adhesion-related genes, particularly LIM and SH3 domain protein 1(LASP1), thereby impairing migration, invasion, and tumorigenic capacity." (PMID 41573677, 2025). "Recent studies have demonstrated that HMGA2 directly regulates ANLN expression by binding to the −3,900 to −3,800 bp DNA fragment of the ANLN gene, driving tumorigenesis in pancreatic carcinoma." (PMID 41573677, 2025). "Experimental studies have confirmed that ANLN overexpression enhances proliferation, colony formation, migration, and invasion of pancreatic carcinoma cells." (PMID 41573677, 2025). "Previous studies have shown that ANLN expression is significantly elevated in pancreatic carcinoma tissues compared to normal pancreatic tissue and pancreatitis tissue." (PMID 41573677, 2025). "First, the functions of MIR600HG, hsa-miR-342-3p and ANLN in pancreatic cancer require further experimental research." (PMID 37741887, 2023).
pancreatic cancer (continued). "LASP1 upregulation partially reverses the tumor-suppressive effect of ANLN downregulation on pancreatic cancer cell progression." (PMID 38144520, 2023). "ANLN contributes to pancreatic cancer progression by regulating the EZH2/miR-218-5p/LASP1 signaling axis." (PMID 38144520, 2023). "The upstream miRNA (hsa-miR-342-3p) and lncRNA (MIR600HG) of ANLN were identified among the DEGs in pancreatic cancer." (PMID 37741887, 2023). "By analyzing the clinical characteristics of patients with different ANLN expression levels, we found that ANLN is related to tumor differentiation in pancreatic cancer." (PMID 37741887, 2023). "In conclusion, we identified the MIR600HG/hsa-miR-342-3p/ANLN network in pancreatic cancer by performing a comprehensive analysis." (PMID 37741887, 2023). "Anillin (ANLN) promoted the progression of pancreatic cancer through inducing EZH2 up-regulation by mediating the miR-218-5p/LASP1 signaling." (PMID 37604837, 2023). "The reduction of ANLN induced apoptosis and thus inhibited tumor proliferation in pancreatic cancer." (PMID 35444699, 2022). "For instance, it was reported that ANLN promoted pancreatic cancer progression by regulating EZH2/miR-218-5p/LASP1 signaling axis." (PMID 34344861, 2021). "Overexpression of ANLN was observedin pancreatic cancer,anddownregulation of ANLN by microRNA inhibited cell aggressiveness." (PMID 34082790, 2021). "In another research about pancreatic cancers, the ANLN level of pancreatic tumours was recorded to increase 20-fold in comparison with normal tissues." (PMID 32560530, 2020). "ANLN expression was significantly upregulated in pancreatic cancer tissues and cell lines, and a high upregulation was implicated with lymph node metastasis, distant metastasis, and poor prognosis in pancreatic cancer." (PMID 32560530, 2020). "ANLN knockdown significantly inhibited the proliferation and migration and invasion of pancreatic cancer cells." (PMID 31395079, 2019). "Further investigation showed that only LASP1 restoration partially reversed the effects of ANLN knockdown on pancreatic cancer cell proliferation, colony formation, cell migration and cell invasion." (PMID 31395079, 2019). "Collectively, these results demonstrated that ANLN promotes pancreatic cancer cell growth, migration and invasion by regulating miR-218-5p/LASP1 signaling axis." (PMID 31395079, 2019). "ANLN contributed to pancreatic cancer progression by regulating EZH2/miR-218-5p/LASP1 signaling axis." (PMID 31395079, 2019). "Further investigation showed that LASP1 restoration partially reversed the effects of ANLN knockdown on pancreatic cancer cell proliferation." (PMID 31395079, 2019). "EZH2 upregulation or miR-218-5p downregulation partially reversed the tumor-suppressive effect of ANLN downregulation on pancreatic cancer cell progression." (PMID 31395079, 2019). "Gene expression microarray analysis and a series of in vitro assays were used to elucidate the mechanisms of ANLN regulating pancreatic cancer progression." (PMID 31395079, 2019). "Based on the GENT database, we showed that both LASP1 and RUVBL1 gene expression were significantly upregulated in pancreatic cancer tissues and were positively correlated with ANLN expression." (PMID 31395079, 2019). "We found that the ANLN expression was significantly upregulated in pancreatic cancer tissues and cell lines." (PMID 31395079, 2019). "LASP1 upregulation partially reversed the tumor-suppressive effect of ANLN downregulation on pancreatic cancer cell progression." (PMID 31395079, 2019). "According to the GENT database, ANLN expression was significantly upregulated in 174 pancreatic cancer tissues compared with that in 62 normal tissues (P < 0.001)." (PMID 31395079, 2019). "Our results showed that ANLN protein expression was significantly increased in the five pancreatic cancer cell lines compared with that in the hTERT-HPNE cell line." (PMID 31395079, 2019).
pancreatic cancer (continued). "EZH2 upregulation induced by ANLN promoted pancreatic cancer cell progression by miR-218-5p/LASP1 signaling axis." (PMID 31395079, 2019). "Cell proliferation, colony formation and transwell assays in vitro and in vivo tumor growth were used to determine the role of ANLN in pancreatic cancer." (PMID 31395079, 2019). "In this study, we showed that ANLN expression was upregulated in pancreatic cancer tissues and cell lines." (PMID 31395079, 2019). "The high expression of ANLN was associated with tumor size, tumor differentiation, TNM stage, lymph node metastasis, distant metastasis and poor prognosis in pancreatic cancer." (PMID 31395079, 2019). "ANLN downregulation inhibited pancreatic cancer cell proliferation, colony formation, migration and invasion." (PMID 31395079, 2019). "In functional assays, miR-218-5p knockdown in pancreatic cancer cells transfected with ANLN RNAi rescued the inhibition of cell proliferation, colony formation, cell migration and cell invasion caused by ANLN knockdown." (PMID 31395079, 2019). "(B) There were significant Pearson correlations of ANLN with LASP1 and ANLN with RUVBL1 in the pancreatic cancer tissues and the normal pancreatic tissues." (PMID 31395079, 2019). "The ANLN mRNA expression in the pancreatic cancer samples with low-level ANLN gene amplification (gain) was markedly increased compared with that in the pancreatic cancer samples with ANLN diploids." (PMID 31395079, 2019). "Consistent with these publicly available data, our results also showed significantly upregulated ANLN expression in pancreatic cancer tissues compared with that in their matched adjacent normal pancreatic tissues." (PMID 31395079, 2019). "For example, ANLN and PRC1 were mutated in cells derived from a malignant melanoma, and RANBP2, TTK, PP2R1A, and CEP192 were mutated in cells from pancreatic cancers." (PMID 27144335, 2016). "Likewise, the progression of pancreatic cancer was influenced by ANLN through the miR-218-5p/LASP1 signaling pathway, which is mediated by EZH2." (PMID 41513610, 2026). "ANLN was related to the poor prognosis, lymph node metastasis, distant metastasis, tumor size, and degree of differentiation in colorectal cancer and pancreatic cancer." (PMID 40161493, 2025). "High ANLN expression is significantly associated with tumor size, differentiation, TNM stage, lymph node metastasis, and distant metastasis in pancreatic carcinoma, and patients with elevated ANLN expression have a poorer overall survival rate compared to those with low expression." (PMID 41573677, 2025). "IHC confirmed the high expression of ANLN in pancreatic cancer." (PMID 37741887, 2023). "ANLN-mediated pancreatic cancer invasion and migration, colony formation, cell proliferation may involve EZH2/miR-218-5p/LASP1 signaling axis." (PMID 37138854, 2023). "WB and IHC were used to confirm the high expression of ANLN in pancreatic cancer." (PMID 37741887, 2023). "In addition, the K–M survival analysis revealed that patients with pancreatic cancer in different histologic grade subgroups presenting high ANLN expression experienced shorter OS." (PMID 37741887, 2023). "Finally, we obtained a new RNA network (MIR600HG/hsa-miR-342-3p/ANLN) related to the prognosis of patients with pancreatic cancer." (PMID 37741887, 2023). "Here, we identified correlations between ANLN expression and the numbers of Th2 and Tem cells, suggesting that ANLN may participate in the immune process of pancreatic cancer through Th2 and Tem cells." (PMID 37741887, 2023). "Nevertheless, the mechanisms that underlie the role of ANLN in the regulation of pancreatic cancer progression have not been fully addressed." (PMID 31395079, 2019). "The ANLN protein expression in pancreatic cancer cell lines was detected by Western blot." (PMID 31395079, 2019). "To determine the function of ANLN in pancreatic cancer, we conducted siRNA-mediated gene silencing." (PMID 31395079, 2019).